ENSG00000249967 (novel protein)
Gene: Protein-coding gene on chromosome 10 (97,584,374 to 97,673,910, forward strand). Ensembl gene ENSG00000249967.
Genetic constraint (gnomAD): Loss-of-function variants: 20 observed, 43.97 expected, observed/expected ratio (o/e) 0.45, 90% interval 0.32 to 0.66. Missense variants: 346 observed, 476.43 expected, observed/expected ratio (o/e) 0.73, 90% interval 0.66 to 0.79. Synonymous variants: 171 observed, 193.07 expected, observed/expected ratio (o/e) 0.89, 90% interval 0.78 to 1.